HK1 (hexokinase 1)
Description:
Catalyzes the phosphorylation of various hexoses, such as D-glucose, D-glucosamine, D-fructose, D-mannose and 2-deoxy-D-glucose, to hexose 6-phosphate (D-glucose 6-phosphate, D-glucosamine 6-phosphate, D-fructose 6-phosphate, D-mannose 6-phosphate and 2-deoxy-D-glucose 6-phosphate, respectively). Does not phosphorylate N-acetyl-D-glucosamine. Mediates the initial step of glycolysis by catalyzing phosphorylation of D-glucose to D-glucose 6-phosphate (By similarity). Involved in innate immunity and inflammation by acting as a pattern recognition receptor for bacterial peptidoglycan. When released in the cytosol, N-acetyl-D-glucosamine component of bacterial peptidoglycan inhibits the hexokinase activity of HK1 and causes its dissociation from mitochondrial outer membrane, thereby activating the NLRP3 inflammasome.
Synonyms: HKI; CNSHA5; HK; HK1-ta; HK1-tb; HK1-tc; HKD; HMSNR; HXK1; NEDVIBA; NMSR; RP79; hexokinase
Tractability: Small molecule: a structure with a bound ligand is known; a high-quality ligand is known; it has a high-quality binding pocket. Antibody: UniProt places it where antibodies can reach, with high confidence. PROTAC: ubiquitination databases record sites on it; its protein half-life has been measured; a small molecule that binds it is known.
Target class: Enzyme
Gene: Protein-coding gene on chromosome 10 (69,269,984 to 69,403,496, forward strand). Ensembl gene ENSG00000156515.
Subcellular location: Mitochondrion outer membrane; Cytoplasm, cytosol
Subcellular location (Human Protein Atlas): Mitochondria
Pathways (Reactome):
Disease: Defective HK1 causes hexokinase deficiency (HK deficiency)
Metabolism: Glycolysis
Metabolism of proteins: Synthesis of GDP-mannose
Gene Ontology:
Molecular function: glucosamine kinase activity; hexokinase activity; mannokinase activity; peptidoglycan binding; protein binding; fructokinase activity; glucokinase activity; ATP binding; D-glucose binding
Biological process: carbohydrate phosphorylation; maintenance of protein location in mitochondrion; protein localization to mitochondrion; canonical glycolysis; fructose 6-phosphate metabolic process; GDP-mannose biosynthetic process; glucose 6-phosphate metabolic process; glucose metabolic process; glycolytic process; mannose metabolic process; carbohydrate derivative metabolic process; carbohydrate metabolic process; hexose metabolic process; intracellular glucose homeostasis; organophosphate metabolic process; positive regulation of cytokine production involved in immune response; positive regulation of interleukin-1 beta production
Cellular component: mitochondrial outer membrane; mitochondrion; cytosol; membrane raft
Genetic constraint (gnomAD): Loss-of-function variants: 26 observed, 93.2 expected, observed/expected ratio (o/e) 0.28, 90% interval 0.2 to 0.39. The upper end of that interval is the gene's LOEUF score, 0.39, which puts it in group 1 of 6, group 1 being the genes least tolerant of losing a copy. Missense variants: 762 observed, 1,265.4 expected, observed/expected ratio (o/e) 0.6, 90% interval 0.57 to 0.64. Synonymous variants: 428 observed, 485.75 expected, observed/expected ratio (o/e) 0.88, 90% interval 0.81 to 0.95.
Homologues: Orthologues: chimpanzee HK1 (98% identical), macaque HK1 (97% identical), dog HK1 (96% identical), rabbit HK1 (94% identical), mouse Hk1 (93% identical), pig HK1 (92% identical), guinea pig HK1 (91% identical), rat Hk1 (91% identical), zebrafish hk1 (85% identical), tropical clawed frog hk1 (84% identical). Paralogues in human: HK2 (73% identical), HKDC1 (71% identical), HK3 (53% identical), GCK (27% identical).
Diseases named in the same sentence as HK1 in open-access papers:
HK1 is named in the same sentence as 243 diseases in open-access papers, as found by Europe PMC text mining. Sharing a sentence is not in itself a finding about the gene and the disease. The quoted sentences say what the papers report.
breast carcinoma (27 papers, 2007 to 2026). "Our studies based on Oncomine databases indicate that in bladder cancer, breast cancer and renal cancer, HK1 messenger RNA level is twofold higher than in corresponding normal tissues." (PMID 28054552, 2017). "On a therapeutic standpoint, hK1 inhibitors showed promising results in models of breast cancer invasion." (PMID 20859288, 2010). "A previous study showed the expression and localisation of hK1 in pancreatic adenocarcinoma of ductal origin and in a breast cancer cell line." (PMID 20859288, 2010). "Evidently, metformin directly inhibits the enzymatic function of HK1 and HK2 in breast cancer cells and markedly reduces tumor glucose consumption and growth." (PMID 26576639, 2015). "Our studies based on Oncomine database show that higher expression of HK1 exists in breast cancer, bladder cancer and renal cancer compared with relative normal tissues." (PMID 28054552, 2017).
pancreatic cancer (21 papers, 2014 to 2025). "In addition, tRF-19-Q1Q89PJZ inhibits the malignant activity of pancreatic cancer cells by regulating HK1 (hexokinase 1)-mediated glycolysis." (PMID 40083327, 2025). "Overexpression of HK1 and HK2 genes was reported in many tumors including colorectal, prostate, breast, lung, gastrointestinal, and pancreatic cancers." (PMID 29504907, 2018). "In pancreatic cancer, KRAS upregulates GLUT1 (glucose transporter 1), as well as HK1 (hexokinase 1), HK2 (hexokinase 2), PFK1 (phosphofructokinase 1) and LDHA (lactate dehydrogenase A), which are key enzymes for the glycolytic processes." (PMID 31225458, 2018). "There are several reports regarding the function of HK1, HK2, and GCK in pancreatic cancer." (PMID 36834681, 2023). "In pancreatic cancer, HNF4α deletion led to a glycolytic energy metabolism transition from typical pancreatic adenocarcinoma to squamous pancreatic cancer, in which Fructose-Bisphosphate Aldolase A (ALDOA), Hexokinase 1 (HK), and Glycogen Synthase Kinase 3 Beta (GSK3β) genes are upregulated." (PMID 36249028, 2022).
glioma (20 papers, 1996 to 2025). A benign or malignant brain and spinal cord tumor that arises from glial cells (astrocytes, oligodendrocytes, ependymal cells). "In glioma, it is known that HK-1, through NK-1R, dose-dependently promotes the migration of U-251 and U-87 glioma cells." (PMID 39941886, 2025). "Previous study has shown that TAC4 mRNA expression in gliomas, indicating a possible involvement of HK-1 in glioma biology." (PMID 36807122, 2023). "SP can also reach glioma cells from the blood, and/or the activation of the NK-1R located in glioma cells can be carried out by other peptides belonging to the tachykinin family (e.g., hemokinin-1 (HK-1))." (PMID 35434136, 2022). "LINC00470 inhibits the ubiquitination of HK1, the first key enzyme in the glycolysis pathway, thereby affecting glycolysis, and inhibiting cell autophagy in gliomas." (PMID 36180956, 2022). "Due to this, we decided to analyze the expression levels of some glycolytic genes in pediatric glioma samples of different grades, and found that the HK1, PFKM, GAPDH, and LDHAL6A genes are overexpressed in human brain glioma biopsies." (PMID 34573317, 2021). "Furthermore, HK-1 phosphorylates p65 and c-Jun and increases both AP-1 and NF-kB activity in U-251 glioma cells." (PMID 39941886, 2025). "In fact, it is known that HK-1 facilitates the proliferation of glioma cells." (PMID 35434136, 2022). "Moreover, a recent study indicated that glioblastoma multiforme, the most common deadly malignant brain tumor, shows increased HK2 expression and downregulated HK1, whereas low-grade glioma and normal brain counterparts predominantly express HK1." (PMID 29721175, 2018). "Furthermore, our study also demonstrated that an increase in HK1, PFKM, and GAPDH expression could be associated with the CNS WHO grading of gliomas." (PMID 34573317, 2021). "Silico analysis and western blot confirmed that HK1 and PKM2 in IDH1 wild-type gliomas were significantly higher than in IDH1 mutant group, while PC was significantly higher in IDH1 mutant gliomas." (PMID 33472598, 2021). "Meanwhile, bioinformatics and western blot were applied to analyze the expression level of metabolic enzymes (e.g. HK1, PKM2, PC) in gliomas." (PMID 33472598, 2021). "Silico analysis showed that HK1 and PKM2 in IDH1wt gliomas were significantly higher than those in IDH1mut group (P = 0.0002 and P<0.0001, respectively), while PC was significantly higher in IDH1mut than in IDH1wt gliomas (P<0.0001)." (PMID 33472598, 2021). "Western blot also confirmed the up-regulation of HK1 and PKM2 in IDH1wt gliomas (P = 0.0004 and P = 0.0003, respectively)." (PMID 33472598, 2021). "Overexpression of either the HK1 or HK2 has been detected in many tumors, including breast, colon and prostate cancers, cervical carcinoma, gastric adenoma, glioma and lymphoma." (PMID 29721175, 2018). "Glioma cells express both SP and HK-1, however, SP is not essential for the viability of glioma cells, and the absence of SP is probably compensated by HK-1 in glioma cells." (PMID 39941886, 2025). "For this reason, the HK1, PFKM, and GAPDH genes could be essential for the progression of glioma to malignant grades, and in this way, they could be useful biomarkers and even targets for the therapy of gliomas." (PMID 34573317, 2021). "The rate-limiting, irreversible and glycolysis-related enzymes hexokinase (HK2 and HK3) and pyruvate kinase (PKM2), but not HK1 or the pyruvate kinase isoform PKLR, were also expressed at lower levels in IDH1MUT glioma compared with IDH1WT glioma." (PMID 28467784, 2017).
hepatocellular carcinoma (18 papers, 2016 to 2025). A malignant tumor that arises from hepatocytes. "In the presence of TSG101, HK1 is secreted extracellularly via vesicles formed by PM budding and further taken up by hepatocellular carcinoma cells to accelerate hepatocellular carcinoma progression by promoting tumour cell glycolysis." (PMID 38485938, 2024). "Further studies have found that PPP2R3A gene overexpression promotes HK1 levels and glycolysis, thereby promoting the proliferation, invasion and migration of hepatocellular carcinoma." (PMID 37124502, 2023). "In hepatocellular carcinoma, miR-139-5p inhibits the expression of glycolytic genes, hexokinase 1 (HK1) and 6-phosphofructo-2-kinase/fructose-2,6-biphosphatase 3 (PFKFB3) expression by directly targeting the ETS1 transcription factor." (PMID 32564010, 2020). "The large extracellular vesicle HK1 is hijacked by hepatocellular carcinoma (HCC) cells, leading to accelerated glycolysis and HCC progression." (PMID 36192599, 2022). "In hepatocellular carcinoma (HCC), lactate accumulation induces H3K18la, which further upregulates SRSF10, indirectly increasing GLUT1, HK1, and LDHA expression, thereby sustaining lactate accumulation and histone lactylation." (PMID 40859309, 2025). "Mammalian cells possess four HK isoforms (HK1, HK2, HK3, and HK4) although HK2 is the predominant enzyme expressed by cancer cells including hepatocellular carcinoma (HCC)." (PMID 37059726, 2023). "Hexokinase 1 is found to be secreted from hepatic stellate cells in large extracellular vesicles in response to TGF-β, and is subsequently taken up by hepatocellular carcinoma cells, where it promotes tumor progression and metastasis." (PMID 36192599, 2022). "HK1 expression was found to be much lower in hepatoma cell lines than in nonhepatoma cell lines analyzed from the Cancer Cell Line Encyclopedia (CCLE) collection." (PMID 36192599, 2022). "MJ has been shown to cleave HK1 and HK2 from VDAC in a dose-dependent manner in the mitochondrial fraction of CT-36 mouse colon carcinoma cells, MOLT-4 human leukemia, BCL1 mouse leukemia, B16 mouse melanoma and HCC hepatocellular carcinoma (LM3, BEL-7402, Hep3B, SMMC-7721)." (PMID 34068337, 2021).
gastric cancer (16 papers, 2013 to 2025). A primary or metastatic malignant neoplasm involving the stomach. "High expression levels of HK1 have been associated with a poor prognosis in patients with colorectal cancer, ovarian cancer, and advanced-stage gastric cancer with lymphatic metastasis." (PMID 37922300, 2023). "Our analysis revealed differential expression of glycolysis-related genes between gastric cancer tissues and normal tissues, with upregulation of PD-L1 and concurrent downregulation of HK1, PDK2, and PDK4." (PMID 38832951, 2024).
colorectal cancer (15 papers, 2016 to 2024). A primary or metastatic malignant neoplasm that affects the colon or rectum. "HK2 inactivation was associated with increased expression of HK1 in colorectal cancer cell lines pointing to the compensation effect." (PMID 28105937, 2016). "HK1 encodes hexokinase 1, which is the first rate-limiting enzyme in glycolysis, is related to the progression of ovarian cancer and colorectal cancer." (PMID 34777463, 2021). "HK2 gene inactivation was associated with increased expression of HK1 in colorectal cancer cells." (PMID 28105937, 2016). "Both colorectal cancer and melanoma cells are more sensitive to HK1 and HK2 deficiency." (PMID 28105937, 2016). "Colorectal cancer cells exhibited enhanced migration and invasion upon ectopic HK1 expression, whereas rat models showed higher lung metastasis." (PMID 38967113, 2024). "In order to silence the expression of HK mRNA in colorectal cancer and melanoma cells, the cell lines were transfected with HK1, HK2, and HK3 shRNA (three shRNAs per each gene: sh#1, sh#2, and sh#3)." (PMID 28105937, 2016). "The extent of carbohydrate metabolic alteration can determine the tissue injury type, and whether it corresponds to benign or malignant proliferative reactive injury, such as overexpression of hexokinase 1 (HK1) in colorectal carcinoma, which appears as an independent prognostic factor." (PMID 33922558, 2021). "However, we can assume that despite the increase in the expression of HK1 in colorectal cancer it may be insufficient to maintain high level of aerobic glycolysis." (PMID 28105937, 2016). "Overexpression of HK1 and HK2 in cancer cells has been previously reported, and HK1 overexpression is a poor prognostic marker in colorectal cancer." (PMID 36497226, 2022). "Taken together, our results suggest HK1 and HK2 genes as the potential molecular targets for colorectal cancer and melanoma therapy." (PMID 28105937, 2016). "We have demonstrated that simultaneous inactivation of HK1 and HK2 was sufficient to decrease proliferation and viability of melanoma and colorectal cancer cells." (PMID 28105937, 2016). "However, we have previously demonstrated a decrease in the expression of HK1 and HK2 in majority of colorectal cancer samples." (PMID 30967137, 2019). "Inactivation of HK2 was followed with up-﻿regulation of HK1 expression in colorectal cancer, but not in melanoma cells." (PMID 28105937, 2016). "The purpose of the present study was to investigate the effect of silencing of hexokinase genes (HK1, HK2, and HK3) in colorectal cancer (HT-29, SW 480, HCT-15, RKO, and HCT 116) and melanoma (MDA-MB-435S and SK-MEL-28) cell lines using short hairpin RNA (shRNA) lentiviral vectors." (PMID 28105937, 2016). "We observed increased expression of HK1 in colorectal cancer cells transfected by vector pLSLP-HK2, but not in melanoma ones; the mRNA and protein levels of HK3 were not altered in all cases." (PMID 28105937, 2016). "We observed increased expression of HK1 in colorectal cancer cells with HK2 gene silencing, but not in melanoma cells." (PMID 28105937, 2016). "The expression levels of HK1 and HK2 were not significantly changed in both colorectal cancer and melanoma cells with HK3 knockdown." (PMID 28105937, 2016).
diabetes (15 papers, 2006 to 2025). "Fourteen of the loci overlapped published GWAS loci for diabetes related traits and were used to identify causal associations of HK1 and PFKFB2 with HbA1c." (PMID 37679740, 2023). "For instance, genes such as TCF7L2 and HK1 located on chromosome 10 have been reported to be significantly associated with the risk of diabetes and HbA1c levels, respectively." (PMID 38274506, 2023). "To date, only one study correlating HK1 variants with HbA1c levels has included patients with diabetes." (PMID 36104811, 2022). "This observed genetic association between glycated hemoglobin levels and HK1 polymorphisms paves the way for further studies of the role of HK1 in hemoglobin glycation, glucose metabolism, and diabetes." (PMID 19096518, 2008). "This observed genetic association between glycated hemoglobin levels and HK1 genetic variants paves the way for further studies of the role of HK1 in glucose metabolism and diabetes." (PMID 19096518, 2008). "Alternatively, genetic variations at HK1 might modulate systemic glucose metabolism, raising the possibility that these variations are associated with the risk of incident diabetes." (PMID 19096518, 2008). "Immunostaining for mitochondrial proteins COX IV and hexokinase-1 (HK1) further corroborated these observations and indicated a marked decrease in mitochondrial proteins by uIRI, which was compounded by underlying diabetes but attenuated by RTN1A knockdown." (PMID 39704174, 2024). "During the normal aging process and in individuals with diabetes, a persistent hexokinase 1 (HK1) relocation from the mitochondria to the cytosol has been described." (PMID 37237939, 2023). "While associations at the GCK, SLC30A8 and G6PC2 loci confirm or extend previous work done on the genetic basis of diabetes or fasting glucose, our replicated findings at HK1 are novel." (PMID 19096518, 2008). "By contrast, the areas under the receiver operating characteristic (ROC) curve (AROC) for DME cases of the serum titer of anti-hexokinase 1 IgG was 0.651 (95% confidence interval [CI], 0.546–0.710) or 0.632 (95% CI, 0.546–0.717) in patients with diabetes or DR, respectively." (PMID 30886155, 2019). "This hypothesis generating genetic observation paves the way for further studies of the role of HK1 in hemoglobin glycation, glucose metabolism and diabetes." (PMID 19096518, 2008). "While associations with the GCK, SLC30A8, and G6PC2 genes have previously been identified in genetic studies of diabetes and blood glucose concentration, the findings at HK1 are novel." (PMID 19096518, 2008).